POSTN (periostin)
Diseases named in the same sentence as POSTN in open-access papers (continued):
Sharing a sentence is not in itself a finding about the gene and the disease.
breast carcinoma (continued). "In breast cancer, periostin was found upregulated at both the mRNA and protein levels." (PMID 22110952, 2011). "However, another study reported a downregulation of POSTN in lung cancer tissues indicating a potential context-dependent tumor suppressor activity of POSTN that could be in line with the association of POSTN overexpression with good prognosis in breast cancer patients observed in the present study." (PMID 21611158, 2011). "Elevated levels of serum POSTN have been reported in breast cancer patients presenting with bone metastases suggesting that POSTN could also be further investigated as a potential metastatic biomarker in the sera of ESCC patients." (PMID 24281036, 2010). "There are several lines of evidence to suggest that POSTN may play a role in the biology of breast cancer." (PMID 17014703, 2006). "Since the estrogen receptor (ER) status is the most important marker in defining the prognosis and treatment of breast cancer, the correlation of POSTN expression with overall survival and disease free survival was analysed in ER-positive and ER-negative subgroups." (PMID 17014703, 2006). "Antibody targeting POSTN exon 17 may be a therapeutic candidate for breast cancer." (PMID 39272982, 2024). "In invasive ductal breast carcinoma, higher POSTN expression levels in cancer-associated fibroblasts (CAFs) have been associated with higher tumor cell grade and shorter overall survival, suggesting that POSTN secreted by fibroblasts may be a marker of breast cancer progression." (PMID 39195230, 2024). "In addition, a DNA inducer that binds to POSTN has been shown to inhibit the growth and metastasis of breast cancer and may be used as a therapeutic tool for breast cancers with POSTNhigh CAFs." (PMID 37143134, 2023). "Inhibition of POSTN may also weaken resistance to chemotherapeutic agents in breast cancer." (PMID 37143134, 2023). "Furthermore, POSTN is highly expressed in bone metastasis of prostate cancer and breast cancer." (PMID 36172351, 2022). "Also, using the pyMT mouse model of breast cancer, it was shown that periostin as the stromal component of the metastatic niche plays an important role in metastasis progression, and a reduction in the number and size of pulmonary metastases was found in periostin −/− mice." (PMID 36224629, 2022). "In addition, they suggested that serum periostin could be detected in early breast cancer patients prior to surgery, and higher serum base-line levels predicted worse long-term survival for specific patient subgroups." (PMID 36224629, 2022). "Also, with chemiluminescence and in situ RNA hybridization, they detected higher serum levels of periostin protein and the periostin gene in stromal tumor tissues of breast cancer patients, and a correlation was seen between increased serum levels of periostin and bone metastasis." (PMID 36224629, 2022). "Methods and Results: We found that POSTN in cancer cells can be detected by using an antibody against the POSTN C-terminal region exon 17 (Ex17 antibody), but not with an antibody against the POSTN N-terminal region exon 12 (Ex12 antibody) in patients with breast cancer." (PMID 33919736, 2021). "Furthermore, targeting periostin with a modified DNA aptamer, PNDA-3, that is capable of binding to periostin with high affinity and inhibiting its function markedly antagonized adhesion, migration, and invasion of breast cancer cells both in vitro and in vivo." (PMID 29758011, 2018). "It has been shown that in breast carcinoma, squamous cell carcinoma and other tumours, blood vessel density in periostin-positive tumours is higher than in periostin-negative tumours with increased tumour invasion and metastasis being reported in these periostin over-expressing tumours." (PMID 30202513, 2018). "Notably, POSTN contributes to the expansion of breast cancer stem cells." (PMID 28526827, 2017).
breast carcinoma (continued). "However, the expression of periostin in the successive steps of breast tumorigenesis and its association with outcome variables have not been well established in breast carcinoma." (PMID 29161296, 2017). "Upregulation of periostin in breast cancer tissues compared to normal tissues and correlation with postoperative distant metastasis and poor prognosis in patients with breast cancer suggests that periostin may be a potential target for therapeutic intervention in the future." (PMID 29161296, 2017). "Additionally, overexpression of POSTN in human mammary epithelial and breast cancer cells resulted in enhanced tumor growth and metastasis, which is similar to a colon cancer cell model where overexpression of POSTN resulted in an increase in the number and size of liver metastases." (PMID 26086719, 2015). "Interestingly, ectopic overexpression of POSTN or recombinant POSTN treatment can induce human mammary epithelial cells and breast cancer cells differentiation into multiple cell lineages that recapitulate part of the multilineage differentiation potentials of MSCs." (PMID 24009721, 2013). "Notably, periostin expression is well correlated with malignant behavior, including growth, invasion, angiogenesis, metastasis and poor survival in ovarian cancer, cholangiocarcinoma, breast cancer, colon cancer, esophageal cancer and pancreatic ductal ADC." (PMID 24273600, 2013). "Moreover, drug sensitivity tests showed that a combination treatment of periostin-specific siRNA with chemotherapy drugs could significantly increase the apoptosis of breast cancer CSC." (PMID 23056395, 2012). "Contrarily, the treatment of quiescent T4-2 breast cancer cells in a 3D system with TGF-β1 and ECM protein periostin resulted in increased tumor size, indicating that TGF-β1, together with periostin, facilitates the exit from the quiescent state." (PMID 40486962, 2025). "These experiments suggest that the co-culture of primary human lung fibroblasts with breast cancer cells leads to a significant and steady increase in gene expression of SPP1, IGF1, POSTN and ACTA2." (PMID 40017592, 2025). "Like POSTN, PDPN is used in humans in the diagnosis of a variety of tumours, and its presence has also been found in CAFs and tumour cells, for example in breast cancer, oesophageal cancer, and lung adenocarcinoma." (PMID 41361308, 2025). "In a genetic mouse model of breast cancer, TGF-β3 increases periostin expression and secretion in lung DTCs, which in turn activates Wnt signaling to allow cancer stem cell maintenance." (PMID 39682261, 2024). "Serum was collected from either naïve C57Bl/6 or POSTN(−/−) mice and used to supplement the serum-free culture medium of growing LLC and polyoma middle T breast cancer cells (PyMT) cells (2% mouse serum)." (PMID 38139195, 2023). "Mature blood vessels, on the other hand, express low levels of periostin and high level of TSP-1, supporting the perivascular quiescence of breast cancer cells." (PMID 37440925, 2023). "With regard to periostin (POSTN), it has been proven that neutralizing it with appropriate antibodies entailed a reduction in breast cancer metastasis to lung tissue." (PMID 35268340, 2022). "Elevated periostin expression is detected in basal-like breast cancer (BLBC), an aggressive subtype of breast cancer that consists mainly of CSCs." (PMID 36224629, 2022). "During pulmonary metastasis of breast cancer, the cancer cells can secrete TGF-β3 to promote periostin (POSTN) produced in SMA+/VIM+ lung fibroblasts to facilitate the formation of metastases." (PMID 34034721, 2021). "Periostin (POSTN) is an extracellular matrix (ECM) protein that is highly expressed in several human cancers, including breast cancer." (PMID 33919736, 2021). "Finally, periostin could predict prognosis in patients with breast cancer." (PMID 32899501, 2020).
breast carcinoma (continued). "Exosomal proteins including fibronectin, surviving, HER2, periostin, and CD47 have been used as markers for the diagnosis of breast cancer." (PMID 33282730, 2020). "Here, we report that periostin, an extracellular matrix protein, was induced upon chemotherapy and tightly correlated with the EMT gene signature and poor prognosis in breast cancer." (PMID 29507310, 2018). "Compared to untreated breast cancer cells, treated breast cancer cells increased their expression of osteoblast cadherin CDH11, RUNX2, osteonectin (SPARC), the bone matrix-remodeling protein periostin, as well as a defined set of “bone-related genes”." (PMID 29867053, 2018). "Periostin was demonstrated to facilitate melanoma metastasis to wounds and to regulate immunosuppressive functions of MDSC during early stages of breast cancer metastasis." (PMID 30061895, 2018). "However, it is not clear whether periostin is produced and secreted by breast cancer cells rather than by cancer-associated stromal cells or by both." (PMID 29161296, 2017). "Although breast cancer is believed to develop from histologically identifiable intraductal lesions known as DCIS, there have been few studies examining periostin expression in breast tumor progression along the spectrum of normal-DCIS-IBC." (PMID 29161296, 2017). "Previous research has found that periostin is highly expressed in various tumors, such as oral cancer, NSCLC, prostate cancer and breast cancer." (PMID 28977942, 2017). "αvβ3, αvβ5, and/or α6β4 integrin complex are cell surface receptors of POSTN in CRC, pancreatic cancer, epithelial ovarian carcinoma, esophageal adenocarcinoma, and breast cancer cells." (PMID 26556874, 2016). "Administering the periostin antibody prolonged cell survival by inhibiting the progression and metastasis of 4T1 cells; therefore, developing the periostin antibody further, including generating a humanized antibody, may provide a new therapeutic agent against breast cancer." (PMID 23056395, 2012). "Periostin expression status was detected in CSC cells and 1,086 breast cancer specimens by Western blot and immunohistochemistry staining, with the CSC ratio determined by immunofluorescence double staining." (PMID 23056395, 2012). "In the current study, we sorted and identified the breast cancer CSC from clinical specimens, observing that periostin was expressed high in breast cancer CSC compared to the control group." (PMID 23056395, 2012). "Hence, periostin may be a potential breast cancer treatment target." (PMID 23056395, 2012). "In conclusion, periostin was found to be related to the CSC and an independent prognostic factor for breast cancer." (PMID 23056395, 2012). "Upregulation of both POSTN and PDPN has been observed in human and canine mammary cancers indicating that for these tumours, in women as in dogs, both proteins as well as Ki67 may have prognostic significance in the course of neoplastic disease." (PMID 41361308, 2025). "We used pathological POSTN with exon 17-expressed 4T1 mice TNBC, where metastases arise spontaneously from primary tumors and progress to lymph nodes and other organs, mirroring human breast cancer." (PMID 39272982, 2024). "Importantly, increases in COL8A1, BGN, COL11A1, POSTN, MMP11 and SORCS2 and decreased LTBP4, PCOLCE2, LRRC17 and SDK1 have been identified in CAS and CAFs from human breast cancer and are consistently perturbed in stroma of canine and human mammary cancer." (PMID 37391533, 2023). "Second, we did not detect the pattern of periostin protein expression in tissue samples from breast cancer patients." (PMID 37716956, 2023). "Strikingly, endothelial-derived thrombospondin-1 in the stable microvasculature induced sustained breast cancer cell quiescence, but this suppressive cue was lost in sprouting neovasculature, where ETC-derived active TGF-β1 and periostin promoted breast tumor growth." (PMID 36917178, 2023).
breast carcinoma (continued). "Furthermore, LINC00520 increases the expression of POSTN, CCNE2, or HSP27 by targeting miR-577, thereby accelerating the progression of breast cancer, non-small cell lung cancer, or colorectal cancer." (PMID 37516879, 2023). "Physical interaction networks however detected only COL3A1, suggesting it could be a gene of interest that CTHRC1, POSTN and MMP13 could use to regulate the tumour matrisome in breast cancers." (PMID 36190948, 2022). "In breast cancer, CTHRC1 gene and protein expression is upregulated with MMP13 and POSTN." (PMID 36190948, 2022). "Periostin (POSTN) is also involved in metastasis of different cancer types by promoting tumor niche formation, especially the CSC niche, and CCL2 was shown to increase the development of CSC in breast cancer by acting on cells in the TME." (PMID 33613850, 2021). "To analyze this phenomenon in detail, we detected the low molecular weight POSTN protein fragment that contained exon 17 from the supernatant of fibroblasts and MBA-MB231 breast cancer cells by Western blotting with the Ex17 antibody, and we used it for the following in vitro experiment." (PMID 33919736, 2021). "In conclusion, we found that a short fragment of POSTN from fibroblasts and breast cancer cells containing exon 17 but not exon 12, binds tightly to wnt3a." (PMID 33919736, 2021). "Breast cancer is characterized by high POSTN expression in cancer epithelial cells when compared with normal tissue." (PMID 29946533, 2018). "Proteomics-based analysis of xenografted breast cancers revealed that highly aggressive and metastatic cancer cell lines produced ECM components such as fibronectin, fibrinogen, laminins, periostin, collagens I, III, IV, V, and VI, transglutaminase 2, and hyaluronan." (PMID 30356678, 2018). "The expression level of periostin mRNA in breast carcinoma tissues was elevated compared with that in corresponding normal tissues and the difference was significant 8.12 ± 7.37 vs. 1.00 ± 0.00, P < 0.05)." (PMID 29161296, 2017). "Moreover, periostin expression was found to be related to the CSC ratio in 1,086 breast cancer specimens (P = 0.001)." (PMID 23056395, 2012). "The present study found that periostin was highly expressed in CSC cells and could be a potential biomarker for the bone metastasis and chemotherapy resistance of breast cancer tumors." (PMID 23056395, 2012). "However, in TAC-operated MCRR mice with an orthotopic breast cancer model, which did not develop any cardiac remodeling and with no affect on tumor growth, there was no increase in cardiac or plasma levels of periostin and CTGF." (PMID 38279150, 2024). "In summary, many studies in breast cancer and other epithelial cancers, such as NSCLC, pancreatic cancer, colon cancer, and prostate cancer, have found that a high expression of periostin in tumor stroma, particularly in CAFs, can be used as a prognostic biomarker." (PMID 36224629, 2022). "If a reference range for normal levels of periostin can be established, PNDA-3 could provide a promising sensor for breast cancer as the aptamer has also been found to inhibit breast cancer growth and metastasis, lending to the possibility for use of the aptamer in sensing and treatment." (PMID 34439139, 2021). "Interestingly, a recent report showed that POSTN is expressed higher in the sorted human CD44+/CD24−/line− breast cancer stem cells compared to the control cells and the levels of POSTN are related to the CSC ratio in human breast cancer specimens." (PMID 24009721, 2013). "Moreover, periostin protein was found to be related to tumor size, histological grade, lymph node metastasis, postoperative distant metastasis, triple-negative breast cancer, and CSC ratio in the 1, 086 breast cancers studied." (PMID 23056395, 2012). "Therefore, POSTN may contribute to breast cancer progression via endowing normal and malignant cells with mesenchymal traits and stem cell-like properties." (PMID 24009721, 2013).
breast carcinoma (continued). "The ECM‐related genes, including MMP1, POSTN, and FN1, have shown higher expression in breast cancer, non‐small lung cancer, bladder cancer, and gastric cancer." (PMID 38639039, 2024). "First, we confirmed that both proteins were expressed in the breast cancer cell lines BT-20 and T-47D; in other cell lines we examined (MCF7, MDA-MB231, and HeLa S3), periostin was present but decorin was not." (PMID 25400079, 2014).